AGFG1 (ArfGAP with FG repeats 1)
Description:
Required for vesicle docking or fusion during acrosome biogenesis (By similarity). May play a role in RNA trafficking or localization. In case of infection by HIV-1, acts as a cofactor for viral Rev and promotes movement of Rev-responsive element-containing RNAs from the nuclear periphery to the cytoplasm. This step is essential for HIV-1 replication.
Synonyms: HRB; RAB; RIP
Tractability: PROTAC: ubiquitination databases record sites on it; its protein half-life has been measured.
Gene: Protein-coding gene on chromosome 2 (227,472,134 to 227,561,217, forward strand). Ensembl gene ENSG00000173744.
Subcellular location: Nucleus; Cytoplasmic vesicle
Subcellular location (Human Protein Atlas): Vesicles
Pathways (Reactome):
Vesicle-mediated transport: Cargo recognition for clathrin-mediated endocytosis; Clathrin-mediated endocytosis
Gene Ontology:
Molecular function: protein binding; RNA binding; GTPase activator activity
Biological process: acrosome assembly; intermediate filament organization; mRNA export from nucleus; spermatid nucleus differentiation
Cellular component: cytoplasmic vesicle; nucleus; cytoplasm; cytosol; nuclear pore; neuronal cell body
Genetic constraint (gnomAD): Loss-of-function variants: 7 observed, 45.99 expected, observed/expected ratio (o/e) 0.15, 90% interval 0.086 to 0.29. The upper end of that interval is the gene's LOEUF score, 0.29, which puts it in group 1 of 6, group 1 being the genes least tolerant of losing a copy. Missense variants: 493 observed, 593 expected, observed/expected ratio (o/e) 0.83, 90% interval 0.77 to 0.9. Synonymous variants: 224 observed, 219.35 expected, observed/expected ratio (o/e) 1.02, 90% interval 0.92 to 1.14.
Homologues: Orthologues: chimpanzee AGFG1 (99% identical), macaque AGFG1 (99% identical), pig AGFG1 (98% identical), dog AGFG1 (97% identical), guinea pig AGFG1 (97% identical), mouse Agfg1 (97% identical), rat Agfg1 (96% identical), rabbit AGFG1 (83% identical), tropical clawed frog agfg1 (68% identical), zebrafish agfg1a (62% identical), zebrafish agfg1b (53% identical). Paralogues in human: AGFG2 (39% identical), SMAP1 (16% identical), ARAP1 (15% identical), ARAP2 (15% identical), ASAP1 (15% identical), ARAP3 (14% identical), ADAP1 (14% identical), ASAP2 (14% identical), SMAP2 (12% identical), ADAP2 (12% identical), ASAP3 (12% identical), ACAP3 (12% identical), and 16 more.
Diseases named in the same sentence as AGFG1 in open-access papers:
AGFG1 is named in the same sentence as 27 diseases in open-access papers, as found by Europe PMC text mining. Sharing a sentence is not in itself a finding about the gene and the disease. The quoted sentences say what the papers report.
asthma (2 papers, 2013 to 2022). "An AHR GWAS among 994 asthma patients found that the most strongly associated SNPs, rs848788 (P-value 7.2E-07) and rs6731443 (P-value 2.5E-06), were in the ITGB5 and AGFG1 genes, respectively." (PMID 23984888, 2013). "Because the nominal replication of AGFG1 associations was observed in LHS, a clinical trial that measured baseline AHR in smokers who did not have current asthma, it is possible that the AGFG1 association reflects biological processes modulating AHR that are not unique to asthma." (PMID 23984888, 2013). "In our study, AGFG1 (ArfGAP with FG repeats 1), including 17 mRNAs and 4 probable alternative promoters, has been reported to play a vital role in diseases, like HIV infection and asthma." (PMID 35178459, 2022). "We utilized data from 994 non-Hispanic white asthma patients to measure the association of single nucleotide polymorphisms (SNPs) with severity of AHR and found that the strongest associations were at variants in two genes: ArfGAP with FG repeats 1 (AGFG1) and integrin, beta 5 (ITGB5)." (PMID 23984888, 2013).
ovarian carcinoma (2 papers, 2015 to 2025). A malignant neoplasm originating from the surface ovarian epithelium. "In our study, several CRGs identified in ovarian cancer, including FGF23 56 and AGFG1 57, are involved in drug metabolism." (PMID 40861807, 2025).
Aortic dissection (1 paper, 2022). Aortic dissection refers to a tear in the intimal layer of the aorta causing a separation between the intima and the medial layers of the aorta. "AGFG1, MCEMP1, IRAK3, KCNE1, and CLEC4D in module M37 were highly connected and strongly linked with AD, suggesting that these genes may help understand the pathogenesis of aortic dissection." (PMID 35178459, 2022).
liver cancer (1 paper, 2025). An epithelial or non-epithelial malignant neoplasm that arises from the liver. "The analysis of TCGA liver cancer data showed that the expressions of AGFG1, IQGAP3, SPINK1, CXCL9, MYO1E, and POF1B were significantly increased in tumor tissues." (PMID 41578779, 2025).
tumor (3 papers, 2014 to 2025). "Normal tissues exhibited higher levels of S100A9, FTCD, POF1B, IL7R, and MYO1E, whereas tumor tissues showed increased expressions of SPINK1, CXCL9, AGFG1, and IQGAP3." (PMID 41578779, 2025).
AGFG1 also shares sentences with these, for which no sentence is quoted: cancer (5 papers); Globozoospermia (2); HIV-1 infection (2); melanoma (2); Pancreatic Cancer (2); pancreatic ductal adenocarcinoma (2); anemia (1); bile duct cancer (1); Charcot-Marie-Tooth disease type 2B (1); glioblastoma multiforme (1); glioma (1); infection (1); infertile (1); influenza (1); lung carcinoma (1); neurodevelopmental disorder (1); pan (1); Parkinsonism (1); rectal cancer (1); triple-negative breast carcinoma (1); tuberculosis (1); viral infection (1).